HMGA1 (high mobility group AT-hook 1)
Diseases named in the same sentence as HMGA1 in open-access papers (continued):
Sharing a sentence is not in itself a finding about the gene and the disease.
tumor (continued). "The tumor volume and weight of xenografts were extensively decreased by HMGA1 knockdown and increased by HMGA1 overexpression." (PMID 33648560, 2021). "In present work, we found that the levels of HMGA1 was positively related with SUZ12 or CCDC43 expression in tumor samples by Spearman’s correlation." (PMID 34167089, 2021). "Our results unequivocally showed that patients with high levels of HMGA1 expression in the tumor had remarkably better OS rates when undergoing treatment with chemotherapy." (PMID 35049679, 2021). "Prior work found that HMGA1 is secreted from TNBC cell lines where it signals through the receptor for advanced glycation end products (RAGE) to foster phenotypes involved in tumor invasion and metastatic progression." (PMID 34572547, 2021). "Here, we showed that HMGA1 was a tumor promotor in pCCA and was correlated with progression and poor prognosis." (PMID 33648560, 2021). "We performed xenograft experiments and assessed the effects of LINC00460 and HMGA1 in LINC00460 knockdown CRC cells by using nude mice to demonstrate their effects on tumor growth in vivo." (PMID 33526059, 2021). "STAT3 functions in inflammation, angiogenesis, and tumor progression, and both HMGA1 and STAT3 are up-regulated and co-expressed in hematologic malignancy." (PMID 34572547, 2021). "Increased HMGA1 expressional levels is closely related with differentiation (P= 0.028), lymph node metastasis (P= 0.004), tumor size (<5 cm3 vs ≥ 5 cm3, P = 0.009), AJCC stage (T1/T2 vs. T3/T4, P = 0.035) and TNM stage (I/II vs. III/IV, P= 0.002)." (PMID 34167089, 2021). "As a result, knockdown of HMGA1 remarkably reduced the tumor volume and weight in both cell line xenografts." (PMID 34716319, 2021). "This somewhat intriguing result can only be explained by our observation that chemotherapy modifies the course of the disease for patients having high expression of HMGA1 in the tumor, increasing the OS of these cases." (PMID 35049679, 2021). "Results showed significant upregulated expression of certain genes like Hgf, Hmga1, Rasgrp1, Sh2b2, Socs1, Socs2, and Socs3 in WT mice tumor compared to its ChREBP systemic knockout tumor." (PMID 34685767, 2021). "HMGA1 facilitated pCCA proliferation, migration, and invasion by promoting tumor stemness and the EMT, which required the involvement of TRIP13." (PMID 33648560, 2021). "It is known that activation of Wnt/β-catenin is required for HMGA1 to promote tumor cell invasion, and conversely, Wnt/β-catenin is involved in tumor cell metastasis by promoting HMGA1 expression." (PMID 34072941, 2021). "HMGA1 re-expression dramatically rescued tumor volume and weights affected by the LINC00460 knockdown." (PMID 33526059, 2021). "With bioinformatics and in vitro/vivo experiments, we showed that HMGA1 induced tumor cell stemness and epithelial-mesenchymal-transition (EMT), and thus facilitated proliferation, migration and invasion by promoting TRIP13 transcription." (PMID 33648560, 2021). "At the same time, higher expression of HCG18, HMGA1, ILF2, and YBX1 was associated with a higher stem cell score and less tumor differentiation." (PMID 34527669, 2021). "In particular, a very recent study demonstrated that FOXM1 physically interacts with the architectural transcription factor HMGA1 to promote tumor angiogenesis cooperatively both in vitro and in vivo models." (PMID 33479222, 2021). "TNBC cells, where extracellular HMGA1 was first described, are characterized by a de-differentiated, mesenchymal like state, which appears to foster tumor initiation and progression." (PMID 34572547, 2021). "Because HMGA1 is overexpressed in most aggressive tumors where it functions in tumor progression, further study of its potential roles in the extracellular space promise to provide important insight relevant to diverse tumors." (PMID 34572547, 2021). "Three genes, including B2M, FGF9 and HMGA1, were also found in the 30 upregulated (in tumor MF) gene list." (PMID 34831413, 2021).
tumor (continued). "Given the parallels between the mechanisms that regulate delamination, migration, proliferation, and survival of neural crest cells and tumor cells, we sought to characterize the expression of Hmga1 during neural crest development." (PMID 32965216, 2020). "We chose to use an inhibitory model to best recapitulate the phenotype we seen in our RNA sequencing datasets where HMGA1-lnc is downregulated in tumor samples." (PMID 33505435, 2020). "HMGA1 regulates the expression of various tumor progression driver genes, such as STAT3, a signal transducer and activator of transcription for which expression is associated to a refractory status in diverse tumors." (PMID 32503270, 2020). "Next, we tested the HMGA1 level in 64 BC tissues and paired 48 adjacent non-tumor tissues by immunohistochemistry." (PMID 32477928, 2020). "In the metastatic scenario, a setting more limited by the availability of paired tumor samples, it would be very appropriate to analyze the changes in the levels and/or subcellular localization of HMGA1 in circulating tumor cells (CTCs)." (PMID 31779212, 2019). "It has been reported that HMGA1 leads to tumour resistance to chemotherapeutic drugs by maintaining the stemness property of the tumour cells." (PMID 30614613, 2019). "The findings provide a more reliable basis for classifying HMGA1 function according to the tumour location." (PMID 30614613, 2019). "Reduced expression of Ki-67 was observed in the tumor mass of MDA-MB-231 cells silenced for HMGA1 and FOXM1." (PMID 31311575, 2019). "This protein overexpression in tumors, together with its low expression in normal adult tissues, makes HMGA1 an excellent target for drug development, as well as an ideal biomarker of tumor progression." (PMID 31779212, 2019). "Considering the histological grade of tumors, a statistically significant augmentation of HMGA1 expression was found in well, moderately and poorly differentiated tumors (G1, G2 and G3, respectively) when compared with tumor-adjacent endometrial samples." (PMID 31096664, 2019). "Nevertheless, our experiments proved that extracellular HMGA1 was able to mediate migration and invasion in tumor cells." (PMID 31779212, 2019). "Various works have shown how different microRNAs modulate the migration and invasion of tumor cells by targeting HMGA1." (PMID 31779212, 2019). "Further studies of the targets of the HMGA1 gene, such as small molecules or drug interventions, will be useful for the clinical treatment of tumours." (PMID 30614613, 2019). "Most of the studies reported that miRNAs, such as miR‐15, miR‐16, miR‐26, miR‐214, miR‐296, miR‐761 and Let‐7a, can inhibit the expression of HMGA1, thereby suppressing tumour progression." (PMID 30614613, 2019). "In this context, several works established that HMGA1 expression is correlated with high tumor grade and metastatization, resistance to therapies and poor prognosis." (PMID 31311575, 2019). "HMGA1 is an oncofoetal gene, and we have a certain understanding of the biological function of HMGA1 based on its activities in various neoplasms." (PMID 30614613, 2019). "In this paper, to characterize HMGA1 comprehensively, research on various types of tumours is discussed to further understanding of the function and mechanism of HMGA1." (PMID 30614613, 2019). "When the expression of HMGA1 is downregulated in aggressive mesenchymal tumor cells (i.e., in MDA-MB-231 and MDA-MB-157), cells became stiffer, while the opposite occurs when HMGA1 is overexpressed in epithelial MCF7 cells." (PMID 31167352, 2019). "Despite gene mutations or rearrangements are rare in malignant solid tumors, HMGA1 is often overexpressed in tumor tissues, and this overexpression frequently correlates with the presence of metastasis and reduced patient survival." (PMID 31779212, 2019). "Our data demonstrate for the first time a direct involvement of HMGA1 in the process of tumor angiogenesis." (PMID 31311575, 2019).
tumor (continued). "In the case of HMGA1, there is also some evidence that links its expression to tumor progression in different tumor types." (PMID 31779212, 2019). "Ever since the discovery of the upregulation of HMGA1 in tumors, several reports have identified HMGA1 as a candidate tumor biomarker." (PMID 31779212, 2019). "As an oncogene, HMGA1 is up‐regulated in many different tumours, including epithelial and mesenchymal tissue‐originated tumours, as shown in this review." (PMID 30614613, 2019). "Correlation of overall survival with HMGA1 and HMGA2 protein expression showed that PDAC patients with tumours that were both HMGA1negative and HMGA2negative had better overall survival than patients whose tumours expressed HMGA1 and/or HMGA2 (p = 0.0022)." (PMID 30228296, 2018). "Due to high levels of expression in aggressive tumors, high mobility group AT-hook 1 (HMGA1) has recently attracted attention as a potential anti-tumor target." (PMID 29581847, 2018). "The expression of HMGA1 was correlated with the tumor aggressiveness, low level of differentiation, resistance to therapies and poor prognosis in the majority of epithelial tumors." (PMID 29980789, 2018). "When TCGA patients with lung SCC were categorised based on expression into ‘HMGA1 high–HEYL low’ and ‘HMGA1 low–HEYL high’ tumours, patients in the former category had a better overall survival (p = 0.00316)." (PMID 29743479, 2018). "In PDAC from KPHetCT;Hmga2+/+ mice the expression of Hmga1 and Hmga2 generally overlapped, with Hmga1 also being highly expressed in advanced primary tumours as well as in metastases." (PMID 30228296, 2018). "If NOTCH1 signalling inhibits HMGA1 in vivo, we would expect an anti-correlation between NOTCH1 activity and HMGA1 expression in human tumour samples." (PMID 29743479, 2018). "Future use of systemic anti-HMGA1 strategies should be cognizant of potential effects of reduced HMGA1 activity in normal epithelia, and, if necessary, adopt methods for targeting HMGA1 therapies specifically to tumor cells." (PMID 29581847, 2018). "HMGA1 has recently become an anti-tumor target due to the correlation of high HMGA1 expression with tumor aggression and mortality." (PMID 29581847, 2018). "A variety of anti-HMGA1 strategies, including small molecules, anti-sense mRNA expression, miRNA expression, and siRNA delivery, have demonstrated promising anti-tumor effects using transformed cells in in vitro systems and xenograft models." (PMID 29581847, 2018). "Mysteriously, HMGA1 proteins are frequently overexpressed in tumor cells, with HMGA1 expression levels often correlated with tumor malignancy." (PMID 26509637, 2016). "This signature showed prognostic value, demonstrated the validity of our approach in shortening the original molecular signature, and highlighted a multifaceted role of HMGA1 proteins in regulating tumor aggressiveness." (PMID 26527623, 2016). "Further, the combination of IL-24 and HMGA1 silencing more strongly inhibited AKT signaling and the associated tumor cell migration and invasion." (PMID 27602961, 2016). "The tissue microarray was performed to investigate the correlation between S100A13 and HMGA1 expression in tumor tissues." (PMID 27008379, 2016). "The combination treatment of IL-24 and HMGA1 siRNA showed the highest inhibition of tumor cell migration (p<0.001) and invasion (p<0.001), compared with all other treatments." (PMID 27602961, 2016). "AKT is a key downstream effector of HMGA1-dependent signaling and provides critical cell survival signals for tumor progression by phosphorylating several proteins involved in cell cycle regulation and pro-apoptotic factors." (PMID 27602961, 2016). "The tumor was also investigated for expression of HMGA2, HMGA1, and MED12 as well as for possible mutations in exon 2 of MED12." (PMID 25621995, 2015). "HMGA1 was down-regulated when HPRT was used as endogenous control gene within the tumour samples (p = 0.0011) compared to the non neoplastic control samples." (PMID 25245141, 2014).
tumor (continued). "HMGA1 was up-regulated when GUSB was used as endogenous control gene within the tumour samples (p = 0.0011) when compared to the non neoplastic samples." (PMID 25245141, 2014). "Among them, SSRP1 and SEPT2 that participate in cell cycle progression or MYCBP, HMGA1 and MT2A involved in cell growth and proliferation and previously linked to tumor progression." (PMID 24870930, 2014). "There is increasing evidence that the high mobility group A1 (HMGA1) protein, which functions as a transcriptional master regulator, plays critical roles in tumor progression." (PMID 23935884, 2013). "Because the EMT plays a central role in differentiation and tumour initiation, we next investigated the impact of HMGA1 expression on the EMT." (PMID 23945276, 2013). "Nevertheless, increasing evidence suggests that a member of this family of proteins, HMGA1, plays a critical role in tumor progression in diverse malignancies." (PMID 23935884, 2013). "Given that the EMT and CSCs play critical roles in tumour metastasis, we next evaluated the impact of HMGA1 depletion on cell motility and invasiveness in vitro." (PMID 23945276, 2013). "In fact, the in vivo effects on metastatic progression were even more pronounced than the effects on primary tumorigenesis, thus highlighting the role of HMGA1 in tumor progression." (PMID 23658826, 2013). "We found that silencing HMGA1 in the aggressive MDA-MB-231 cells leads to a dramatic decrease in tumor growth following mammary fat pad implantation." (PMID 23658826, 2013). "Cox multivariate analysis revealed that the HMGA1 gene signature behaves as a significant (p<0.05) independent prognostic factor together with ER status, lymph node impairment and tumour size." (PMID 23945276, 2013). "HMGA1 is expressed in embryonic fibroblasts and in several cell types (bone marrow cells, macrophages, tumor cells) of adults." (PMID 22606223, 2012). "In limiting dilution tumorigenicity experiments, knock-down of HMGA1 blocked tumor formation when 104 or 105 cells were injected, whereas tumors formed in the control cells." (PMID 22276142, 2012). "Inhibiting HMGA1 expression blocks tumorigenesis at limiting dilutions, consistent with depletion of tumor-initiator cells in the knock-down cells." (PMID 22276142, 2012). "Taken together, our studies suggest that HMGA1 promotes tumor progression through transcriptional networks that facilitate metastatic progression and a stem-like state, at least in part, by inducing the Twist1 and Vimentin, while repressing E-cadherin." (PMID 22276142, 2012). "To determine how HMGA1 orchestrates tumor progression and stem cell phenotypes, we investigated expression of genes that have been previously shown to be important in EMT, development, and tumor initiator cells." (PMID 22276142, 2012). "To better elucidate the role of HMGA1 in tumor progression, we used genome-wide expression profile analysis in our HMGA1a (herein referred to as HMGA1) transgenic mouse model for lymphoid malignancy." (PMID 22053823, 2011). "Repressing a suppressor of metastases represents a previously undescribed pathway through which HMGA1 promotes tumor progression." (PMID 22053823, 2011). "Together, these studies implicate HMGA1 as a key regulator in tumor progression, poor differentiation, and refractory disease." (PMID 22053823, 2011). "Early in tumor development, we found that genes involved in the inflammatory response are dysregulated by HMGA1." (PMID 22053823, 2011). "In GEP NETs, a high proportion of tumours (38 of 55, 69%) was detected with nuclear HMGA1 protein expression." (PMID 19156147, 2009). "Higher expression of HMGA1 and 2 was frequently observed in tumours with let-7 significant reduction (53, 42%, respectively)." (PMID 19156147, 2009). "Consistent with this view, both Hmga1 transgenic mice and Hmga1 knockout mice develop haematologic malignant tumours." (PMID 17311013, 2007).
tumor (continued). "Furthermore, we examined NPM1 and HMGA1 co-expression in the tumor samples, revealing a notable 20.69% co-expression rate." (PMID 41145488, 2025). "Definitive mechanistic clarification will require experimental studies such as CRISPR/Cas9-mediated knockdown or overexpression, rescue assays to confirm pathway dependency, and in vivo tumor models to evaluate how HMGA1 influences immune cell dynamics within the tumor microenvironment." (PMID 41463532, 2025). "First, we developed a comprehensive computational framework to simultaneously analyze: (i) the genetic and epigenetic determinants of HMGA1 dysregulation; (ii) its impact on tumor immunity and patient prognosis; and (iii) its potential as a predictive biomarker for therapy response." (PMID 41463532, 2025). "To complement these bulk transcriptomic analyses and gain cellular-level insights, we leveraged single-cell RNA sequencing (scRNA-seq) data from the TISCH database, validating HMGA1 expression patterns across tumor-infiltrating immune and stromal cells populations." (PMID 41463532, 2025). "While these decreases could inhibit tumor growth and spread, HMGA1, a protein involved in cell proliferation and gene regulation, was upregulated." (PMID 40429900, 2025). "Notably, HMGA1 and NUDT16 were highly expressed in radioresistant cell lines, and targeting NUDT16-HMGA1 pathway significantly enhanced the sensitivity of tumor cells to chemotherapy and IR treatment." (PMID 40288645, 2025). "Thus, it is interesting to investigate the impact of HMGA1 on tumor growth or chemotherapeutic sensitivity by affecting tumor cell metabolism in the future." (PMID 38383528, 2024). "Interestingly, HMGA1 was deleted in the tumor region of the NR group, and its protein level is known to be significantly increased in serous epithelial ovarian cancer." (PMID 39135097, 2024). "Additionally, p‐ATM expression was increased in tumours with HMGA1 knockdown, and the combination of HMGA1 depletion and olaparib treatment further increased p‐ATM levels, suggesting excessive accumulation of DSB damage." (PMID 39690136, 2024). "Additionally, we found that expression of FOXM1 and HMGA1 was noticeably increased in a tumor grade-dependent manner compared to other TFs (p-value < 0.001, one-way ANOVA)." (PMID 39594773, 2024). "Additionally, a detailed exploration is conducted into the interactive pathways between key subgroups, such as the C3 HMGA1+ Myofibroblasts in myofibroblasts, and tumor cells within EPCs." (PMID 38562930, 2024). "A549 tumor mouse xenografts were constructed by injection with si-HMGA1 or si-HMGA1 NC." (PMID 38706894, 2024). "Our analysis revealed a conspicuous overexpression of HMGA1 in tumor tissues of ESCC patients." (PMID 38725843, 2024). "We found that HMGA1 was highly expressed in tumor tissues and enriched in immuno-cold tumors, indicating that HMGA1 could shape immuno-cold TME and promote immunosuppression." (PMID 38329444, 2024). "Overexpression of HMGA1 is known to promote tumor cells proliferation, invasion, and migration." (PMID 38383528, 2024). "HMGA1 plays an important role in tumor metastasis and EMT progress." (PMID 38405614, 2024). "Moreover, we utilized syngeneic allograft tumor models and genetically engineered mice of HMGA1 to induce ESCC and validated that depletion of HMGA1 promotes ferroptosis and restores the sensitivity of ESCC to DDP, and hence enhances the therapeutic efficacy." (PMID 38383528, 2024). "Finally, we showed that silencing HMGA1 enhanced tumour sensitivity to olaparib, providing a potential new approach to overcoming olaparib resistance in EC patients." (PMID 39690136, 2024). "It was reported that HMGA1 suppression inhibits tumor progression by blocking cell cycle." (PMID 39080260, 2024).